TFPI (tissue factor pathway inhibitor)
Diseases named in the same sentence as TFPI in open-access papers (continued):
Sharing a sentence is not in itself a finding about the gene and the disease.
breast carcinoma (continued). "In the present study, we have characterized the mRNA and protein expression of two isoforms of TFPI (α and β) and also TF, in a panel of breast cancer cell lines in comparison to normal endothelial cells." (PMID 23320987, 2013). "Overexpression of TFPI in breast cancer cells affected the expression of mRNAs and miRNAs involved in processes facilitating cancer cell growth and immunologic response, possibly by signal transduction involving the EGFR pathway." (PMID 23071754, 2012). "We recently reported that overexpression of TFPIα or TFPIβ in SK-BR-3 breast cancer cells resulted in pro-apoptotic and anti-proliferative effects of either isoform in vitro, but the mechanism behind the effect of TFPI is poorly understood." (PMID 23071754, 2012). "In the present study, we investigated how downregulation of TFPI would affect the growth and metastatic abilities of human breast cancer cells in vitro, and the possible mechanisms involved." (PMID 21849050, 2011). "In a recent study, we demonstrated a pro-apoptotic effect of both TFPIα and TFPIβ in breast cancer cells in vitro, while corresponding downregulation of endogenous TFPI resulted in reduced apoptotic activity." (PMID 21849050, 2011). "In summary, downregulation of TFPI induced intracellular tyrosine signaling and increased the self-sustained growth and metastatic abilities of breast cancer cell lines in vitro." (PMID 21849050, 2011). "Elevated levels of plasma TFPI in cancer patients have previously been reported, and TFPI expression was demonstrated in several tumors, including breast cancer tissue and cells, indicating a possible involvement of TFPI in cancer biology." (PMID 21849050, 2011). "In the present study, we demonstrate that stable downregulation of both isoforms of TFPI and TFPIβ alone enhanced the metastatic growth of breast cancer cells by increasing cell spreading, migration and invasion." (PMID 21849050, 2011). "The constructs of TFPI-2 promoter luciferase-reporter bearing respective genetic variations were transiently transfected into breast cancer cells and the luciferase activities were measured according to the manufacture's instruction." (PMID 18053161, 2007). "Since previous studies using the overexpression of murine Sdc-1 in human breast cancer cells provided insights into its role in cell-cycle progression, we performed cell cycle analysis for Sdc-1-overexpressing cells with respect to TFPI treatment." (PMID 36980251, 2023). "Overexpression of TFPI was recently known to trigger apoptosis in SK-BR-3 breast cancer cells." (PMID 36900315, 2023). "Since IGF-1R has been described as an anti-apoptotic factor in breast cancer cells, increased apoptosis observed in TFPI-stimulated MDA-MB-231 cells may be a consequence of diminished IGF-1R levels as a result of TF pathway inhibition." (PMID 36980251, 2023). "Moreover, TFPI inhibited breast cancer cell proliferation and invasion by downregulating the extracellular signal-regulated kinase (ERK)/p38 mitogen-activated protein kinases (MAPK) signaling pathway." (PMID 37238908, 2023). "Moreover, stable downregulation of both isoforms of TFPI was found to increase the metastatic growth of breast cancer cells by boosting cell proliferation, motility, and invasion." (PMID 36900315, 2023). "TFPI has been reported to be related to survival in breast cancer." (PMID 36556252, 2022). "Interestingly, estrogen-treated individuals, patients with breast cancer and lung cancer have reduced levels of TFPI and exhibited venous thrombosis." (PMID 34315984, 2021). "Tissue factor pathway inhibitor (TFPI) is an endogenous inhibitor of tissue factor-induced blood coagulation, and its expression has been demonstrated in smooth muscle cells, monocytes, platelets, and several breast cancer cell lines." (PMID 34115774, 2021). "Here, we report several indications that TFPI have clinical significance in breast cancer." (PMID 25882602, 2015).
breast carcinoma (continued). "Moreover, total TFPI (α + β), TFPIα and TFPIβ expression levels were differentially distributed among the five molecular breast cancer subtypes; with higher expression in the HER2-enriched and the normal-like group, and lower in luminal B tumors." (PMID 25882602, 2015). "We now report that breast cancer patients with low tumor expression of both isoforms of TFPI had worse outcome in terms of both overall- and relapse free survival compared to patients with higher TFPI expression." (PMID 25882602, 2015). "Additionally, tumor-expressed TFPI and TF were positively correlated, which is in line with our previous findings in breast cancer cell lines that TFPI expression follows TF expression and the aggressive basal-like tumor subtype." (PMID 25882602, 2015). "Endothelial cells account for most of the TFPI production, but TFPI expression has also been demonstrated in other cell types, such as monocytes, smooth muscle cells, platelets, and in several breast cancer cell lines." (PMID 25617766, 2015). "In this study, we showed that high TF-expressing breast cancer cells could bind to immobilized TFPI in vitro under shear in a FVIIa- and TF-dependent manner." (PMID 25849335, 2015). "GPI-attached TFPI located at the surface of breast cancer cells inhibited TF activity and could possibly reduce TF signaling and breast cancer cell growth locally, indicating a therapeutic potential of the TFPIβ isoform." (PMID 23320987, 2013). "Overexpression of TFPI in breast cancer cells conducted in previous experiments resulted in an increase in TF, PAR-1, and PAR-2 mRNA levels, which may indicate that TFPI is in fact able to affect TF signaling." (PMID 23320987, 2013). "Moreover, PI-PLC pre-treatment of HCAEC cells followed by heparin released 50% more free TFPI into the supernatant and reduced cell lysate levels additionally compared to heparin alone as seen in the Sum102 breast cancer cells." (PMID 23320987, 2013). "To further explain the role of TFPI in malignant disease, we have in the present study aimed to characterize TFPI by investigating the expression and localization of TFPIα and TFPIβ, and also the relation to TF expression and activity, in a panel of breast cancer cell lines." (PMID 23320987, 2013). "Preliminary results from our laboratory indicate that estrogen decreases TFPI expression in ER positive breast cancer cells, which could contribute to the estrogen-driven growth of such tumors." (PMID 23071754, 2012). "We recently showed that shRNA mediated downregulation of TFPI inhibited apoptosis, while ectopic overexpression of TFPI induced apoptosis in breast cancer cells, supporting this hypothesis." (PMID 21849050, 2011). "We recently reported that downregulation of TFPI inhibited apoptosis in a breast cancer cell line." (PMID 21849050, 2011). "Moreover, the previous finding that SDC3 mediates cell surface localization of TFPI in breast cancer and vascular cells may have contributed to this impact on Src signaling." (PMID 41148827, 2025). "Therefore, it is possible that erythroblasts may employ a unique pathway to increase TFPI expression, which differs from that of breast cancer cells and endothelial cells." (PMID 38729948, 2024). "Furthermore, the expression of TFPI also varies throughout the vasculature system depending on location and organ, with highest expressions in lung vasculature, one of the main sites of breast cancer metastasis." (PMID 25849335, 2015). "Thus, GPI-attached TFPI expressed by breast cancer cells was able to directly interfere with the TF activity on the cell surface and may therefore have implications for the pro-cancer nature of TF." (PMID 23320987, 2013). "In the present study, we examined the potential impact of anticancer treatment on the TF, TFPI, t-PA, PAI-1 antigen concentrations and TF, TFPI activities in breast cancer patients." (PMID 37240751, 2023).
breast carcinoma (continued). "In this study, as a first step, we investigated the prognostic role of haemostatic parameters,TFPI, TF, t-PA and PAI-1, as potential prognostic factors of breast cancer recurrence and OS." (PMID 37240751, 2023). "Similarly, in vitro experiments, IHC, and in situ hybridization studies have revealed the presence of TFPI antigen in cancer cells in most cases of colon cancer and in all cases of breast cancer, which may suggest a role for TFPI in the biology of the neoplasms." (PMID 33947134, 2021). "We found that high-TF-expressing breast cancer cells, MDA-MB-231 (with a TF density of 460,000/cell), but not low TF-expressing MCF-7 (with a TF density of 1,400/cell), adhered to recombinant TFPI, under static and shear conditions." (PMID 25849335, 2015). "Therefore, it seems that increased tumor expression of TFPI may be beneficial in breast cancer." (PMID 25882602, 2015). "Heparin treatment resulted in the release of TFPI from the Sum102 and MDA-MB-231 breast cancer cells in a similar manner to that observed in normal endothelial cells in this and a previously study." (PMID 23320987, 2013). "The breast cancer cell lines Sum102 and MDA-MB-231, possessing high TFPI expression, were further analyzed to determine the nature of any cell-associated TFPI." (PMID 23320987, 2013). "Based on these results, we postulate that TFPI, TF, t-PA and PAI-1 may act as biomarkers for monitoring therapy in patients with breast cancer." (PMID 37240751, 2023). "However, in the current study, EVs thrombogenicity, as reflected in the levels of EVs: TF, TF/TFPI ratio, and EVs EPCR (count as soluble EPCR, a pro-thrombotic marker) were found to be similar in breast cancer and colorectal patients." (PMID 33108394, 2020). "We found that, similar to J82 bladder tumor cells, high TF-expressing (MDA-MB-231), but not low TF-expressing (MCF-7), breast cancer cells bound to immobilized recombinant TFPI under static conditions in a FVIIa-dependent manner." (PMID 25849335, 2015). "The expression of both isoforms of TFPI varied considerably among the breast cancer cell lines tested, from no expression in Sum149 cells to levels above or in the same range as normal endothelial cells in Sum102 and MDA-MB-231 cells." (PMID 23320987, 2013). "In contrast to what was reported previously for HUVECs, serum was not necessary for the release of TFPIα by heparin in the breast cancer cells or HCAECs, although serum did increase the amount of TFPI released by heparin." (PMID 23320987, 2013). "Heparin treatment released TFPI from breast cancer cells without reducing cell surface levels, which is consistent with what was observed in endothelial cells in this and other studies." (PMID 23320987, 2013). "PI-PLC treatment released both TFPIα and TFPIβ from the breast cancer cell membrane and increased TF activity on the cell surface, showing TF-FVIIa inhibitory activity of the glycosylphosphatidylinositol- (GPI-) anchored TFPI." (PMID 23320987, 2013). "Stable downregulation of both isoforms of TFPI in Sum102 and MDA-MB-231 breast cancer cells." (PMID 21849050, 2011). "Moreover, SDC3 mediates localization of TFPI—a molecule endowed with tumor suppressor activity —to the surface of endothelial, smooth muscle, and breast cancer cells, which may contribute to an antitumoral effect of SDC3 in the breast cancer microenvironment." (PMID 41148827, 2025). "On the other hand, HIFs downregulate several proteins such as tissue factor pathway inhibitor (TFPI) through binding to negative HREs sequences, which were identified as 5′-GACATG-3′ and 5′-AAACAGGA-3′ in the human breast cancer MCF-7 cell line." (PMID 31682627, 2019). "Sequential treatment with PI-PLC followed by heparin did not reduce TFPI cell surface levels any further than PI-PLC alone (data not shown), which is equivalent to the observations in the breast cancer cell lines." (PMID 23320987, 2013).
COVID-19 (20 papers, 2021 to 2025). A disease caused by infection with severe acute respiratory syndrome coronavirus 2. "Our data showed that the TFPI level in PLWH with COVID-19 was higher than that in both the HCs and PLWH." (PMID 40568587, 2025). "An increase in TFPI has previously been shown in moderately ill COVID-19 patients compared to healthy subjects." (PMID 37239041, 2023). "Circulating TF was higher in COVID-19 patients than septic shock patients, while TFPI was similarly elevated in both groups." (PMID 35111777, 2021). "Specifically, markers supporting a procoagulant endothelial phenotype including Angpt-2, P selectin, thrombomodulin, and TFPI were all elevated in severe disease compared with moderate COVID-19 in our cohort." (PMID 34506304, 2021). "Our results do not show a COVID-19-associated depletion of TFPI or a significant correlation between TFPI and NETosis markers." (PMID 37239041, 2023). "Moreover, in the acute COVID-19 patients, the effect of the neutralization of TFPI activity accounted for an increase of 3.9 ± 2.8 pM/mL in FXa production (+39%), which was lower compared to that measured in the HSs (7.1 ± 2.2 pM/mL FXa, +63%)." (PMID 37759632, 2023). "Knowing that plasma TFPI level is significantly higher in CVD and other pathologies, including COVID-19, where TFPI increase is universally accepted to reflect endotheliopathy, it is crucially important to correlate the plasma levels of ADTRP with those of TFPI in the same sample groups." (PMID 33923232, 2021). "Loss of the constitutive endothelial anticoagulants such as TFPI, EPCR, and thrombomodulin is an important component of the prothrombotic endothelial transformation and may be an underappreciated driver of COVID-19 coagulopathy." (PMID 34506304, 2021). "A better understanding of critical COVID-19 pathophysiology suggests potential therapeutic strategies, in particular recombinant IL-1ra and recombinant TFPI could modulate these two over-expressed pathways." (PMID 35111777, 2021). "Plasma from patients with severe or moderate COVID-19 induced significant upregulation of genes encoding tissue factor, E selectin, and Angpt-2 and concurrently decreased the expression of antithrombotic genes encoding endothelial protein C receptor (EPCR), TFPI, and thrombomodulin." (PMID 34506304, 2021). "Based on these results, we suggested potential therapeutic strategies, in particular, recombinant IL-1ra and recombinant tissue factor pathway inhibitor (TFPI), in order to modulate these two overstimulated pathways in COVID-19 patients." (PMID 36008932, 2022). "On focusing on prothrombotic mechanisms, we noted COVID-19 patients in the ICU had higher coagulation factor III (CFIII) and tissue factor pathway inhibitor (TFPI) supporting a prothrombotic state compared to controls." (PMID 35502320, 2022). "Eight genes associated with platelet activation and pro-thrombosis were upregulated in COVID-19 patients: MPIG6B, HBB, HPSE, CD40LG, STXBP3, CLEC1B, TFPI and GNAS." (PMID 35477940, 2022). "Our study found increased antithrombin and plasminogen in pre-COVID-19 dengue patients, but not TFPI, compared to post-COVID-19 patients and controls." (PMID 41305453, 2025). "These unexpected observations in the CAT assay may be attributed to elevated plasma levels of anticoagulant factors, such as thrombomodulin (TM) – a tissue factor pathway inhibitor (TFPI), existing in certain COVID-19 patients, as shown by published data." (PMID 38327640, 2024). "Low plasma levels of TFPIα (full-length TFPI) correlate with prothrombotic diseases, including DVT/VTE, coronary artery disease (CAD), ischemic stroke, peripheral artery occlusive disease, and, lately, COVID-19." (PMID 33923232, 2021). "COVID-19 patients had higher plasma TFPI levels than pulmonary-infected non-COVID-19 patients." (PMID 37239041, 2023).
COVID-19 (continued). "Interestingly, coagulation factor III and TFPI (also part of the coagulation pathway) were not different between the two groups, consistent with the observation that coagulopathy is a more prominent feature of severe COVID-19 than severe influenza infection." (PMID 34529726, 2021). "However, in COVID-19 patients, we observed lower plasma levels of D-dimers, vWF-A2, sICAM1, sTREM1, VEGF, and sP-selectin as compared to non-COVID-19 patients, and a non-significant difference for plasma levels of sTM, TFPI, uPA, CXCL4, PDGF-AA and PDGF-AB/BB." (PMID 34422854, 2021).